SPARC (secreted protein acidic and cysteine rich)
Diseases named in the same sentence as SPARC in open-access papers (continued):
Sharing a sentence is not in itself a finding about the gene and the disease.
influenza (1 paper, 2020). An acute viral infection of the respiratory tract, occurring in isolated cases, in epidemics, or in pandemics; it is caused by serologically different strains of viruses (influenzaviruses) designated A, B, and C, has a 3-day incubation period, and usually lasts for 3 to 10 days. "Third, the underlying mechanisms of MCEMP1 and SPARC genes contributing to the development of protective immunity after influenza vaccination should have been rigorously verified in multidimensions, especially the regulation of effector cytokines (CXCL 8/IL-8, Granzyme-B)." (PMID 33343577, 2020). "The integrated functional analysis revealed MCEMP1 and SPARC as the hub genes during the development of safe and effective immunity related to influenza vaccines in the top age-related module and top gender-related module, respectively." (PMID 33343577, 2020). "This is probably the first study regarding the correlation of these two genes (MCEMP1, SPARC) with individual traits and immune responses in the development of effective immunity against influenza after QIVs inoculation." (PMID 33343577, 2020). "From these results, it can be concluded that the MCEMP1 and SPARC genes may have an effect on the development of protective humoral and cell immunity against influenza in the elderly." (PMID 33343577, 2020). "Furthermore, the transcriptional expression level of SPARC was obviously higher in the female group than in the male group, reaching the peak in the former group at day 3 and in the latter group at day 28, implying higher humoral antibody and immune responses to influenza vaccines in the females." (PMID 33343577, 2020). "Furthermore, due to the insufficient research on potential biomarkers for the evaluation of influenza vaccine efficacy and safety, MCEMP1 and SPARC genes in our study may provide a good reference for further studies." (PMID 33343577, 2020).
injury (1 paper, 2020). Damage inflicted on the body as the direct or indirect result of an external force, with or without disruption of structural continuity. "This study demonstrated that SPARC was involved in glutamate-induced nerve injury." (PMID 33584170, 2020).
juvenile-onset primary open-angle glaucoma (1 paper, 2010). "Moreover, as the GLC1M locus was identified in a pedigree of juvenile-onset primary open-angle glaucoma (JPOAG) with high IOP, we investigated the involvement of SPARC variants in JPOAG by mutation screening and copy number analysis." (PMID 21042566, 2010).
large cell carcinoma (1 paper, 2020). A malignant epithelial neoplasm composed of large, atypical cells. "The methylation status of the SPARC gene evaluated by QMSP firstly in four NSCLC cell lines: A549, H2228, H1573 (ADC) and H460 (large cell carcinoma, LCC) and in the two non-neoplastic cell lines NL20 and MRC-5." (PMID 32580473, 2020).
Left ventricular diastolic dysfunction (1 paper, 2020). Abnormal function of the left ventricule during left ventricular relaxation and filling. "However, despite SPARC-induced positive effect in the acute phase of MI, detrimental effects in pressure overload have been suggested to be induced by the increased SPARC-mediated collagen cross-linking and aging, as it causes left ventricular diastolic dysfunction." (PMID 33192583, 2020).
lobular breast carcinomas (1 paper, 2022). "Elevated SPARC expression was found in invasive ductal or lobular breast carcinomas, compared with ductal or lobular breast carcinomas (P < 0.05)." (PMID 35211625, 2022).
malaria (1 paper, 2018). Malaria is a serious and sometimes fatal disease caused by a parasite that commonly infects a certain type of mosquito which feeds on humans. "Six representative examples, showing both increased (ADSSL1, CEBPA, CRP, LBP) and decreased protein levels (CCL5, SPARC) in malaria patients compared to controls are shown in." (PMID 30442134, 2018). "Out of the six proteins, three were identified as showing increased levels (CRP, CSF1, LBP) in malaria patients compared to controls while the remaining three displayed decreased levels (CCL5, CTSD, SPARC)." (PMID 30442134, 2018).
malignant mesothelioma (1 paper, 2016). A malignant neoplasm of the pleura or peritoneum, arising from mesothelial cells. "Malignant mesothelioma cells were screened for the expression of markers associated with the osteoblast cell lineage; RUNX2, SPARC and SPP1." (PMID 27886205, 2016).
malignant pleural mesothelioma (1 paper, 2017). A malignant neoplasm that arises from mesothelial cells in the pleura and shows a diffuse growth pattern. "In malignant pleural mesothelioma, both tumor cells and tumor stromal cells expressed SPARC." (PMID 29156791, 2017).
metastatic prostate carcinoma (1 paper, 2014). A carcinoma that arises from the prostate gland and has spread to other anatomic sites. "The staining for SPARC in the epithelial tumoral component correlated with high Gleason scores of the samples, which agrees with the known association of metastatic prostate cancer with high Gleason indexes of primary tumors." (PMID 25331979, 2014).
Mycobacterium infection (1 paper, 2021). Infections with bacteria of the genus Mycobacterium. "This is in contrast to mycobacterium infection where, despite SPARC’s critical role in granuloma formation, SPARC deficiency leads to enhanced immune responses." (PMID 33633185, 2021).
myocarditis (1 paper, 2019). Myocarditis is a condition that is characterized by inflammation of the heart muscle (myocardium). "In conclusion, we demonstrate a novel inotropic function for SPARC in the heart, with a potential therapeutic application when myocyte contractile function is diminished such as that caused by a myocarditis-related cardiac injury." (PMID 30933983, 2019). "In this study we demonstrate a novel inotropic function for extracellular SPARC in the healthy heart as well as in the diseased state after myocarditis-induced cardiac dysfunction." (PMID 30933983, 2019).
neck cancer (1 paper, 2021). "A previous study demonstrated that the overexpression of SPARC may be associated with response to nanoparticle albumin-bound paclitaxel (nab-paclitaxel in neck cancer)." (PMID 34456964, 2021).
neoplastic syndrome (1 paper, 2016). A broad classification for disorders in which the development of neoplasms typically occur in association with a characteristic set of signs or symptoms. "Although the present study is the first mention of pro-inflammatory regulation of SPARC expression in cerebral endothelia, other CNS injury models and neoplastic syndromes have highlighted the association between inflammation and SPARC-enriched blood vessels." (PMID 27581191, 2016).
nephritis (1 paper, 2025). Inflammation of renal tissue. "Transient increases in SPARC, which correlate with collagen deposition in the initial stage of interstitial fibrosis, have been reported in an animal model of nephritis." (PMID 40362650, 2025).
odontogenic cyst (1 paper, 2024). A cyst in the jaw that arises from tissues of tooth development. "Additionally, to determine whether SPARC is associated with aggressive behavior in OKCs, SPARC expression in OKCs was compared with radicular cysts (RCs), dentigerous cysts (DCs) and calcifying odontogenic cysts (COCs)." (PMID 38347494, 2024). "Comparing among the four groups of odontogenic cysts, we found that OKCs showed significantly higher fibroblast SPARC expression than those of RCs, DCs and COCs." (PMID 38347494, 2024). "Compared among the four groups of odontogenic cysts, SPARC expression in OKCs was significantly higher than those of RCs, DCs and COCs." (PMID 38347494, 2024). "Compared between 4 groups of odontogenic cysts, SPARC expression in OKCs was significantly higher than those of RCs (P < 0.001), DCs (P < 0.001) and COCs (P = 0.001)." (PMID 38347494, 2024). "Little is known about SPARC expression in odontogenic keratocyst (OKC), an odontogenic cyst with an aggressive nature." (PMID 38347494, 2024). "Unlike other odontogenic cysts, COCs showed SPARC expression not only in fibroblasts of the cystic wall, but also cells in the epithelial lining." (PMID 38347494, 2024). "Additionally, to determine whether SPARC is associated with aggressive behavior in OKCs, we compared SPARC expression in OKCs with other odontogenic cysts with no or less aggressive behavior including radicular cysts (RCs), dentigerous cysts (DCs) and calcifying odontogenic cysts (COCs)." (PMID 38347494, 2024).
odontogenic keratocyst (1 paper, 2024). "It is of interest that SPARC may also be involved in aggressive behavior of odontogenic keratocysts (OKCs)." (PMID 38347494, 2024).
osteomyelitis (1 paper, 2021). An acute or chronic inflammation of the bone and its structures due to infection with pyogenic bacteria. "A study on osteomyelitis-associated genes indicates that chickens suffering from BCO showed downregulated level of Runt-related transcription factor (RUNX2) and secreted protein acidic and cysteine rich (SPARC) genes." (PMID 34434965, 2021). "We hypothesize that the dysbiosis of the blood microbiome results in the downregulation of RUNX2 and SPARC in BCO chickens, which further leads to osteomyelitis." (PMID 34434965, 2021).
pancreatic diseases (1 paper, 2016). "SPARC is therefore involved in a number of pancreatic diseases, and SPARC expression and function in the pancreas is relatively well characterised." (PMID 27886258, 2016).
pancreatitis (1 paper, 2021). Inflammation of the pancreas. "For example, in methylation of SPARC differentiated early-stage PDA from pancreatitis patients, high methylation of SPARC and NPTX2 is associated with late-stage or metastatic patients and worse survival outcomes." (PMID 34439749, 2021).
papillary adenocarcinoma (1 paper, 2017). A morphologic variant of adenocarcinoma. "Although a few SPARC positive cells were observed in the normal gastric mucosa, much more SPARC positive cells were found in the interstitium of papillary adenocarcinoma and tubular adenocarcinoma." (PMID 29156791, 2017).
Paralysis (1 paper, 2016). Paralysis of voluntary muscles means loss of contraction due to interruption of one or more motor pathways from the brain to the muscle fibers. "In both remitting and non-remitting EAE models, SPARC-like 1/SPARC mRNA and protein ratios inversely correlated with clinical paralysis severity scores." (PMID 27581191, 2016).
periodontal disease (1 paper, 2020). "It is found that lack of SPARC/osteonectin causes a reduction in total collagen, and its production is known to be affected by periodontal disease." (PMID 32121498, 2020).
periodontitis (1 paper, 2020). An acute or chronic inflammatory process that affects the tissues that surround and support the teeth. "Another biomarker implicated in increased collagen turnover is ‘secreted protein acidic and rich in cysteine’ (SPARC) since it has been found in high levels in periodontitis patients who present with lesser amounts of bone destruction." (PMID 32121498, 2020).
periodontosis (1 paper, 2011). "In transgenic animals, SPARC has also been demonstrated to associate with other age- and matrix-related disorders, including periodontosis and decrease in myocardial stiffness." (PMID 21949685, 2011).
pheochromocytoma (1 paper, 2019). "In order to investigate the effects of the NGFβ and SPARC interaction on NGFβ-induced neuronal differentiation of PC12 rat pheochromocytoma, we initially examined the NGFβ-dependent activation of p44/p42 MAPK (ERK1/2) as its phosphorylated state." (PMID 30934765, 2019). "Therefore, we examined the interactions of adiponectin and SPARC with NGF using a surface plasmon resonance (SPR) method and their effects on NGF-dependent morphological changes in PC12 rat pheochromocytoma." (PMID 30934765, 2019).
Photophobia (1 paper, 2022). Excessive sensitivity to light with the sensation of discomfort or pain in the eyes due to exposure to bright light. "GO disease analysis also found that SPARC was correlated with electroretinogram abnormality, photophobia, rod-cone dystrophy, and disorder of the eye." (PMID 35721704, 2022).
pneumoconiosis (1 paper, 2014). An occupational lung disorder caused by inhalation of dust particles. "In the present study, we investigated the association between the potential functional polymorphisms in SPARC and coal workers' pneumoconiosis (CWP) risk in a Chinese population." (PMID 25126876, 2014). "SPARC participates in collagen deposition probably through three mechanisms in the pathogenesis of pneumoconiosis." (PMID 25126876, 2014).
polyp (1 paper, 2019). A usually exophytic mass attached to the underlying tissue by a broad base or a thin stalk. "Research investigating VF tissue, identified genes differently expressed in polyp lesions versus Reinke’s edema, and found SPARC significantly upregulated in VF polyps, suggesting its reparative role in regulating the polyp microenvironment." (PMID 31014251, 2019).
Renal cyst (1 paper, 2013). A fluid filled sac in the kidney. "It was also higher than the plasma and urine concentrations of SPARC in ADPKD patients, patients with simple renal cysts and normal control patients." (PMID 23516489, 2013).
Sepsis (1 paper, 2015). Sepsis is defined as life-threatening organ dysfunction caused by a dysregulated host response to infection. "Both sepsis-induced matrix production and the downregulating effect of compstatin treatment were confirmed by semi-quantitative histochemical analysis after immunostaining for procollagen-3 and SPARC." (PMID 26337158, 2015).
skin aging (1 paper, 2023). The gradual irreversible changes in structure of skin that occur as a result of the passage of time.. "We inferred that the decline in SPARC expression in aged skin contributes to process of skin aging by negatively affecting ECM integrity in fibroblasts." (PMID 37569556, 2023). "Based on these results, we suggest that SPARC plays a role in maintaining the integrity of the ECM by regulating ECM components, thus contributing to retarding the process of intrinsic skin aging." (PMID 37569556, 2023). "Therefore, we suggest that SPARC is an important factor for improving ECM integrity and slowing intrinsic skin aging." (PMID 37569556, 2023).
small cell lung carcinoma (1 paper, 2017). Small cell lung cancer (SCLC) is a highly aggressive malignant neoplasm, accounting for 10-15% of lung cancer cases, characterized byrapid growth, and early metastasis. "Our results reveal that knockdown of WNK1 decreases SPARC treatment-induced migration and reverses the transition of the mesenchymal phenotype in non-small cell lung cancer cell lines H1299 and CL1-5." (PMID 28969021, 2017).
tendinopathy (1 paper, 2023). "Also, upregulation of genes encoding proteoglycans (BGN) glycoproteins (TNC, FN1, SPARC), integrins (ITGB1), and growth factors has been reported in tendinopathy patients." (PMID 38001919, 2023).
thrombocytopaenia (1 paper, 2018). "Thrombocytes have also been identified to secrete SPARC, thus decreased levels of SPARC could also be the result of thrombocytopaenia." (PMID 30442134, 2018).
tongue cancer (1 paper, 2017). A malignant neoplasm affecting the tongue. "Previous reports suggest that SPARC serves as a prognostic marker for the stage II tongue carcinoma and is positively correlated with lymph node metastasis and survival rate in stage II tongue squamous cell carcinoma." (PMID 28718842, 2017).
Ureteral obstruction (1 paper, 2026). Obstruction of the flow of urine through the ureter. "SPARC expression strongly correlates with fibrosis severity in both human CKD biopsies and murine models of unilateral ureteral obstruction (UUO) and ischemia-reperfusion injury (IRI)." (PMID 42212322, 2026).
uterine sarcomas (1 paper, 2023). "Polo-like kinase 4 (PLK4), Secreted Protein, Acidic and Rich in Cysteine (SPARC) Related Modular Calcium Binding 2 (SMOC2), Special AT-rich Sequence-Binding protein 2 (SATB2), or Forkhead box P3 (FOXP3) + T cells have all been suggested as prognostic indicators for uterine sarcomas." (PMID 37173887, 2023).